SEMA3A (semaphorin 3A)
Description:
Involved in the development of the olfactory system and in neuronal control of puberty. Induces the collapse and paralysis of neuronal growth cones. Could serve as a ligand that guides specific growth cones by a motility-inhibiting mechanism. Binds to the complex neuropilin-1/plexin-1.
Synonyms: SEMAD; SEMA1; SemD; coll-1; Hsema-I; COLL1; HH16; Hsema-III; SEMAIII; SEMAL
Tractability: Antibody: its Gene Ontology location is reachable by antibodies, with high confidence; UniProt places it where antibodies can reach, with medium confidence; UniProt predicts a signal peptide or a membrane-spanning region. PROTAC: ubiquitination databases record sites on it.
Gene: Protein-coding gene on chromosome 7 (83,955,777 to 84,492,939, reverse strand). Ensembl gene ENSG00000075213.
Subcellular location: Secreted
Subcellular location (Human Protein Atlas): Vesicles; Predicted to be secreted
Pathways (Reactome):
Developmental Biology: CRMPs in Sema3A signaling; SEMA3A-Plexin repulsion signaling by inhibiting Integrin adhesion; Sema3A PAK dependent Axon repulsion
Gene Ontology:
Molecular function: chemorepellent activity; neuropilin binding; semaphorin receptor binding
Biological process: negative regulation of neuron projection development; olfactory bulb development; regulation of axon extension involved in axon guidance; axon extension involved in axon guidance; axon guidance; axonogenesis involved in innervation; basal dendrite arborization; branchiomotor neuron axon guidance; facial nerve structural organization; motor neuron axon guidance; negative chemotaxis; nerve development; neural crest cell migration; neural crest cell migration involved in autonomic nervous system development; neuron migration; positive regulation of cell migration; positive regulation of JNK cascade; semaphorin-plexin signaling pathway; sensory system development; sympathetic ganglion development; sympathetic nervous system development; sympathetic neuron projection extension; sympathetic neuron projection guidance; trigeminal nerve structural organization; forebrain development
Cellular component: axon; extracellular region; glutamatergic synapse; plasma membrane
Genetic constraint (gnomAD): Loss-of-function variants: 19 observed, 61.56 expected, observed/expected ratio (o/e) 0.31, 90% interval 0.21 to 0.45. The upper end of that interval is the gene's LOEUF score, 0.45, which puts it in group 2 of 6, group 1 being the genes least tolerant of losing a copy. Missense variants: 585 observed, 762.72 expected, observed/expected ratio (o/e) 0.77, 90% interval 0.72 to 0.82. Synonymous variants: 240 observed, 260.42 expected, observed/expected ratio (o/e) 0.92, 90% interval 0.83 to 1.03.
Homologues: Orthologues: chimpanzee SEMA3A (99% identical), macaque SEMA3A (98% identical), pig SEMA3A (96% identical), rat Sema3a (96% identical), dog SEMA3A (95% identical), mouse Sema3a (95% identical), guinea pig SEMA3A (93% identical), rabbit SEMA3A (91% identical), tropical clawed frog sema3a (85% identical), zebrafish sema3ab (76% identical). Paralogues in human: SEMA3D (53% identical), SEMA3B (52% identical), SEMA3E (47% identical), SEMA3F (47% identical), SEMA3G (45% identical), SEMA3C (43% identical), SEMA4D (32% identical), SEMA4C (30% identical), SEMA4G (30% identical), SEMA4B (29% identical), SEMA5B (28% identical), SEMA6A (28% identical), and 7 more.
Diseases named in the same sentence as SEMA3A in open-access papers:
SEMA3A is named in the same sentence as 253 diseases in open-access papers, as found by Europe PMC text mining. Sharing a sentence is not in itself a finding about the gene and the disease. The quoted sentences say what the papers report.
breast cancer (23 papers, 2005 to 2024). A primary or metastatic malignant neoplasm involving the breast. "Loss of SEMA3A was also associated with higher-grade (grade III) ductal carcinomas and poor survival in a panel of 2878 breast cancer patients, associating the loss of SEMA3A with aggressive breast cancer." (PMID 37685898, 2023). "NP1 complexing with plexin-A1 involving both VEGF and SEMA3a has been implicated in the chemotaxis of breast cancer cell lines." (PMID 25889301, 2015). "Ccl17 and Cxcr3 increased in mammary tumors that protects cancer cell survival and induce tumor growth to promote breast cancer lung metastasis Hypoxia-induced chemokine Sema3a stimulates tumor-associated macrophages to the alternative type (M2), leading to pro-tumor immunity." (PMID 35768767, 2022). "While existing research has shed some light on SEMA3A's involvement in various cancers, including breast cancer, a more in-depth investigation is necessary to fully understand its implications in this specific context and its possible clinical impact." (PMID 38263416, 2024). "Immunohistochemical evaluation was performed on 98 breast cancer patients' tumor specimens, and SEMA3A expression was assessed in tumor cells and vessels." (PMID 38263416, 2024). "The objective of our study was to evaluate SEMA3A expression in breast cancer and to investigate its distribution across breast cancer subtypes." (PMID 38263416, 2024). "In conclusion, our study provides valuable insights into the complex role of SEMA3A in breast cancer biology." (PMID 38263416, 2024). "This study aimed to evaluate SEMA3A expression in breast cancer and investigate its distribution across breast cancer subtypes: luminal A, luminal B, HER2-positive, and triple-negative breast cancer (TNBC)." (PMID 38263416, 2024). "We analyzed correlations between level of SEMA3A expression and various immunohistochemical factors of breast cancer subtypes." (PMID 38263416, 2024). "The proven strongly positive expression of SEMA3A in breast cancer tumor cells, its involvement in vascular development and tumor biology suggests potential importance of SEMA3A as therapeutic target in breast cancer treatment." (PMID 38263416, 2024). "Sema3A has also been shown to inhibit the migration of breast cancer cells and invasiveness of prostate cancer cells in vitro." (PMID 35347234, 2022). "Recruitment of TAMs into hypoxic niches occurs in a hypoxia-induced Semaphorin 3A (Sema3A)-dependent manner through VEGF-R1 phosphorylation in a mouse model of breast cancer." (PMID 33968034, 2021). "SEMA3A is identified as a potent tumor suppressor in some cancers (breast cancer and prostate cancer), inhibits endothelial cell adhesion and migration, induces the collapse of the actin cytoskeleton and apoptosis, reduces angiogenesis in vitro." (PMID 32842711, 2020). "SEMA3A has been identified as a candidate tumor suppressor and it is often found to be downregulated in different types of cancer, such as prostate cancer, breast cancer, and glioma." (PMID 32842711, 2020). "In breast cancer cells, sema3A was found to regulate the phosphorylation and nuclear translocation of phosphatase and tensin homolog (PTEN) and the activation of the forkhead transcription factor FOXO-3a." (PMID 30696103, 2019). "This was the first study to investigate the clinical significance of the miR-362-5p/Sema3A axis in breast cancer." (PMID 31929841, 2019). "Sema3A protein was an independent prognostic factor for breast cancer patients in the HBre-Duc150Sur-02 tissue array." (PMID 31929841, 2019). "Conversely, over-expression of PTEN and FOXO-3a was found to enhance sema3A expression resulting in inhibition of breast cancer cells migration." (PMID 30696103, 2019). "It was found to involve a novel mechanism of regulating tumor suppression by Sema3A in coordination with a chain of tumor-suppressor genes, which in turn inhibits breast cancer cell migration, tumor growth, and angiogenesis." (PMID 30155491, 2018).
breast cancer (continued). "Sema3A has been found to increase integrin receptor expression and cell adhesion in breast cancer cells and inhibit breast cancer cell motility." (PMID 28182100, 2017). "Our observations suggest that Sema3A stimulates changes in MDA-MB-231 breast carcinoma cell motility, spreading, and focal adhesions in a substrate-specific manner." (PMID 28182100, 2017). "Sema3A has been shown to increase integrin expression and cell adhesion in breast carcinoma cells, while our results demonstrate that Sema3A increases integrin signaling, as indicated by increased pFAK397 at focal adhesions, on collagen and fibronectin." (PMID 28182100, 2017). "Cell motility was assessed using a scratch assay by culturing MDA-MB-231 breast carcinoma cells on a substratum coated with increasing concentrations of collagen in the presence of either IgG1 Fc control or Sema3A." (PMID 28182100, 2017). "In particular, semaphorin 3A (Sema3A) displays tumor suppressing effects on prostate and breast carcinoma cell migration and invasion in vitro." (PMID 28182100, 2017). "In fact, studies have shown that breast carcinoma cells secrete Sema3A which signals through an autocrine mechanism to upregulate α2β1 integrin expression." (PMID 28182100, 2017). "We propose that Sema3A alters focal adhesions to modulate breast carcinoma cell migration and spreading on substrata coated with different concentrations of ECM." (PMID 28182100, 2017). "Our findings are consistent with other studies that showed Sema3A treatment of breast carcinoma cells increases RhoA activity to inhibit cell migration." (PMID 28182100, 2017). "SEMA3A can inhibit the proliferation of malignant mesothelial cells, decrease the adhesion or migration of prostate or breast cancer cells, and promote apoptosis in leukemic T cells." (PMID 22926477, 2012). "For example, in breast cancer, SEMA3A can inhibit cell attachment and cell migration by affecting the activation or stabilisation of surface integrins." (PMID 22926477, 2012). "We found that MDA-MB-231 breast cancer derived cells express predominantly np1, a receptor for sema3A and sema3D, but very little np2 if at all." (PMID 18818766, 2008). "Neuropilin-1 has also been implicated in chemotaxis of breast cancer cell lines through autocrine pathways involving both VEGF and SEMA3a by complexing with plexin-A1." (PMID 15956974, 2005). "Further studies are warranted to comprehensively evaluate the role of SEMA3A in breast cancer." (PMID 38263416, 2024). "Further investigations are warranted to fully comprehend the role of SEMA3A in breast cancer biology, which may lead to the identification of novel therapeutic targets and personalized treatment strategies for breast cancer patients." (PMID 38263416, 2024). "The results of our study provided evidence of positive expression of SEMA3A in breast cancer." (PMID 38263416, 2024). "They suggested that SEMA3A expression could potentially influence the metastatic cascade and contribute to the complex mechanisms of breast cancer metastasis." (PMID 38263416, 2024). "Analysis indicated positive expression of SEMA3A in breast cancer cells in 60 out of 98 cases." (PMID 38263416, 2024). "We speculated that miR-362-5p participated in the carcinogenesis and development of breast cancer by regulating its target gene Sema3A." (PMID 31929841, 2019). "Decreased Sema3A expression has been proposed to lead to a trend of decreasing effectiveness in promoting osteoblast formation in bone metastases of human breast cancer cells, suggesting that decreased Sema3A may play an important role in bone loss." (PMID 29457037, 2017). "Sema3A inhibits cell adhesion in prostate cancer cells as well as dorsal root ganglion neurons but promotes integrin activation and cell adhesion in breast cancer cells." (PMID 28182100, 2017). "Indeed, reduced expression of Sema3A is correlated with breast carcinoma and melanoma progression in humans." (PMID 28182100, 2017).
breast cancer (continued). "SEMA3A inhibits cell adhesion and migration through an increase in integrin-α2β1 levels and through the promotion of RhoA translation via a mechanism that involves eIF4E in breast cancer models." (PMID 26755661, 2016). "Additionally, we sought to explore how immunohistochemical subtypes of breast cancer might impact SEMA3A expression." (PMID 38263416, 2024). "Therefore, the negative correlation between SEMA3A and steroid receptor levels indicates that elevated SEMA3A expression may have a detrimental impact on prognosis in breast cancer." (PMID 38263416, 2024). "In addition, Sema3A is considered to function as a tumor suppressor as reduced Sema3A expression is correlated with breast carcinoma and melanoma progression in humans, while overexpression of Sema3A suppresses tumor growth and metastasis in vivo using xenograft mouse models." (PMID 28182100, 2017). "In our previous study of transcriptome analysis of mammary tumors of PyMTSB2−/− mice, the expression levels of cancer immune modulated genes (ANXA3, CCL17, CXCL13, CXCR3, IFN-γ, NR4A1, and SEMA3a) were significantly changed." (PMID 38956496, 2024). "The antitumour effect of SEMA3A was defined in an experimental mouse breast cancer model, using BALB/c mice transplanted with 4T1 cells overexpressing SEMA3A, compared to control 4T1 cells." (PMID 37685898, 2023). "It is shown that SEMA3A interacted with NRP1 to mediate MelCAM expression, leading to the suppression of breast cancer cell growth and angiogenesis." (PMID 37701532, 2023). "Gene of Ccl17, Cxcl13, Cxcr3, IFN-γ, and Sema3a, were significantly decreased while the Anxa3 and Nr4a1 were significantly upregulated in SB2−/−;PyMT mammary tumors." (PMID 35768767, 2022). "Sema3A inhibits the migration and spreading of MDA-MB-231 breast cancer cells as well as their ability to form colonies in soft agar, and it also inhibits similarly the invasiveness of prostate cancer cells in in-vitro assays." (PMID 30696103, 2019). "This study provides evidence implicating a role for Sema3A signaling in modulating cell-substratum adhesions as integrin expression, ECM deposition, and Sema3A expression are altered during mammary tumor progression." (PMID 28182100, 2017). "miR-362-5p/Sema3A may provide a promising therapeutic pathway and represents a candidate therapeutic target of TNBC subtype breast cancer." (PMID 31929841, 2019). "Therefore, we assessed whether Sema3A alters the motility and spreading of MDA-MB-231 breast carcinoma cells on substrata coated with different concentrations of ECM through changes in cell-substratum adhesion dynamics." (PMID 28182100, 2017). "To put this prediction to the test we expressed sema3A and sema3F in MDA-MB-468 breast cancer cells, which do not express np1, np2 or PlexD1." (PMID 18818766, 2008).
glioma (18 papers, 2008 to 2025). A benign or malignant brain and spinal cord tumor that arises from glial cells (astrocytes, oligodendrocytes, ependymal cells). "While previous studies have shown that Nrp1 is expressed in high and low grade glioma biopsies, our study is the first to show that higher expression of Nrp1, PlxnA1 and Sema3A are all associated with decreased survival in both GBM and LGG cohorts." (PMID 33302912, 2020). "SEMA3A expression was also associated with poor survival in cervix and low grad gliomas." (PMID 38609390, 2024). "Semaphorin 3A (sema3A) has been implicated to promote the infiltration and spread of glioma-derived cells in an autocrine fashion and is overexpressed in a subset of gliomas in patients." (PMID 32914058, 2018). "A genome-wide association study suggested that increased European ancestry in non-European population might be associated with the occurrence of glioma and identified four novel susceptibility variants, including 7q21.11 (SEMA3A), 11p11.12 (Intergenic), 12q24.21 (RBM19) and 20p12.13 (HAO1, BMP2)." (PMID 33430813, 2021). "SEMA3A (Semaphorin 3A) is known to promote the invasion and migration of glioma cells, while NRP2 (Neuropilin-2) regulates the migratory ability of glioma cells in response to SEMA3A." (PMID 36231068, 2022). "Previous work suggested that semaphorin 3C, plexin A2, plexin D1, and Nrp1 form a complex in glioma stem cells, whereas numerous studies have indicated the interaction of semaphorin 3A, plexins, and Nrp1." (PMID 34270956, 2021). "Although the median survival for Low grade glioma patients with low expression of Sema3A/Nrp1/PlxnA1 is significantly greater than those with high expression, the curves do converge at long-term endpoints." (PMID 33302912, 2020). "Sema3A was not a member of the cluster of regulation of cell growth; however it was recently reported that Sema3A is involved in cell proliferation in both glioma and glioblastoma cells." (PMID 30862786, 2019). "Sema3A is secreted by glioma-derived cells in vesicles, which have been shown to directly increase vascular permeability by interacting with Nrp1 on endothelial cells in xenograft mouse models." (PMID 32914058, 2018). "These signalings are consistent with the protumorigenic role of Sema3A in promoting glioma cell dispersal." (PMID 23050142, 2012). "Silencing Sema3A expression by RNA interference resulted in a significant suppression in migration and an alteration in glioma cell morphology in a Rac1-dependent manner." (PMID 23050142, 2012). "In contrast to Sema3A, in vitro data revealed that Sema3F inhibits glioma cell migration via RhoA inactivation by p190 RhoGAP." (PMID 23050142, 2012). "Taken together, these results demonstrate that the Sema3A/NRP1 signaling axis is associated with poor prognosis, is particularly elevated in the mesenchymal subtype, and is correlated with TGF-β activity in a large glioma cohort." (PMID 37788099, 2023). "In addition, mRNA expression levels of NRP1 in glioma specimens positively correlated with those of Sema3A or TGF-βR1, as determined by The Cancer Genome Atlas (TCGA) data analysis." (PMID 37788099, 2023). "We assessed the effects of Sema3A or NRP1 knockdown on glioma-forming ability in vivo." (PMID 37788099, 2023). "Association between the levels of Sema3A/NRP1 and survival of patients with glioma." (PMID 37788099, 2023). "Finally, we examined TCGA survival data in both low grade glioma and glioblastoma based off expression levels of these three transcripts: Sema3A, Nrp1, PlxnA1." (PMID 33302912, 2020). "Similarly, a protumorigenic role of Sema3A was implicated by its overexpression in human GBM specimens, which acts in an autocrine fashion to promote glioma cell dispersal through neuropilin-1." (PMID 23050142, 2012). "As VEGF165 binds to NRP2, competition between SEMA3B/3G and VEGF165 for binding to NRP2 might exist in gliomas as demonstrated for SEMA3A and NRP1 in ECs." (PMID 18781179, 2008).